ATP2A2 (ATPase sarcoplasmic/endoplasmic reticulum Ca2+ transporting 2)
Diseases named in the same sentence as ATP2A2 in open-access papers (continued):
Sharing a sentence is not in itself a finding about the gene and the disease.
Darier disease (continued). "We also hypothesize that the loss-of-function (LOF) mechanism of ATP2A2 mutations demonstrated in Darier’s disease can explain the relationship between ER Ca2+ storage and glutamate-induced excitotoxicity." (PMID 35517826, 2022). "Similarly, ATP2A2 mutations account for the development of the Darier disease (keratosis follicularis), a severe skin disorder characterized by skin wart-like blemishes, due to loss of adhesion between epidermal cells." (PMID 33407740, 2021). "Our predicted gene ATP2A2 has been identified in clinical cases of Darier's disease and may directly contribute to epilepsy associated symptoms, validating the efficacy and accuracy of our prediction." (PMID 28255556, 2017). "The genes disturbed by the CNVs mainly involve the SH2B1, TUFM, ATP2A1, and ATP2A2 genes, of which mutations of the single ATP2A2 gene in Darier disease have been found to be connected to the neuropsychiatric abnormalities frequently observed in Darier disease." (PMID 28680393, 2017). "Given the extensive functional knowledge on ATP2A2 and the role of ATP2A2 variants in human Darier disease, we nonetheless think that our data strongly suggest that the SINE insertion may be considered a candidate causative variant for the phenotype in the affected dog." (PMID 32354065, 2020). "It is due to the heterozygous missense mutation p.(Pro602Leu) in the ATPase sarcoplasmic/endoplasmic reticulum Ca2+ transporting 2 (ATP2A2) gene, which is also involved in Darier disease (DD), and is therefore considered an allelic form of DD." (PMID 42205461, 2026). "The mosaic form of Darier disease is caused by mutations in the ATP2A2 gene on chromosome 12q23-24.1, resulting in calcium-ATPase (SERCA2) cation pump dysfunction in the endoplasmic reticulum." (PMID 38406622, 2024). "Darier disease, akin to HHD due to a similar cellular phenotype stemming from mutations in ATP2A2, was found to have an increased risk of T1D." (PMID 38014829, 2023). "Whole genome sequencing of the affected dog was performed, and the functional candidate genes for Darier disease (ATP2A2) and Hailey-Hailey disease (ATP2C1) were investigated." (PMID 32354065, 2020). "Many independent genetic variants in ATP2A2 and ATP2C1 in human patients with Darier disease or Hailey-Hailey disease have been described." (PMID 32354065, 2020). "The affected proteins/disorders included Atp2a2 (Darier’s disease), Eef2 and Itpr1 (Spinocerebellar ataxia), Atp1a3 (Dystonia Parkinsonism)." (PMID 28893375, 2017). "This is the first study to use whole exome sequencing to screen the ATP2A2 gene in a cohort of 28 clinically diagnosed Darier disease patients." (PMID 29028823, 2017). "Human ortholog, ATP2A2 (OMIM: 108740) is reported to cause an autosomal dominant disorder called, Darier disease and null mutations in mouse demonstrate reduced myocyte contractility." (PMID 26815362, 2016). "Mutation of the ATP2A2 gene encoding sarco-endoplasmic reticulum calcium ATPase 2 (SERCA2) was linked to Darier disease more than 2 decades ago; however, there remain no targeted therapies for this disorder causing recurrent skin blistering and infections." (PMID 37561594, 2023). "OWK can be distinguished from Darriers disease by the absence of germline mutations in ATP2A2 (the gene responsible for Darier disease) and the absence of SERCA2 protein." (PMID 35626429, 2022). "Considering the essential roles of ATP2A2 in Ca2+ signaling, mood disorders and schizophrenia in Darier’s disease patients, which are supposed to result from a pleiotropic effect of the LOF mutations in ATP2A2, a study of brain-specific KO mice for Atp2a2 would be useful to clarify the mechanisms." (PMID 34104969, 2021). "None of our patients were previously diagnosed with Darier disease, but ATP2A2 was one of the target genes associated with the thyroid signaling pathway but also with the pathways of neurodegeneration in the present study, suggesting a link between these two pathways in the pathogenesis of MDD." (PMID 39457478, 2024).
Darier disease (continued). "Dark-skinned individuals with Darier disease (DAR; OMIM#124200), a genodermatosis caused by mutations in the ATP2A2 gene altering cell adhesion through defects in calcium signaling, can sometimes exhibit hypopigmented macules." (PMID 38589876, 2024). "In humans, Darier disease (MIM #124200), also called Darier-White disease or keratosis follicularis, is inherited as an autosomal dominant trait and caused by heterozygous variants in the ATP2A2 gene encoding the endoplasmic/sarcoplasmic reticulum Ca2+-ATPase 2 (SERCA2)." (PMID 32354065, 2020). "Since Atp2a2-knockout mice do not phenocopy its pathology, we established a human tissue model of Darier disease to elucidate its pathogenesis and identify potential therapies." (PMID 37561594, 2023). "A subsequent study found depletion of the ATP2A2-gated stores in cultured keratinocytes from one of these dogs and suggested that these dogs had Darier disease and not Hailey-Hailey disease as previously reported." (PMID 32354065, 2020).
cardiac hypertrophy (27 papers, 2009 to 2026). "Reports indicate THRB's regulation of genes linked to myocardial hypertrophy, including Myh6, Adrb1 and Atp2a2,28, 29 highlighting its role in myocardial remodelling and explaining the downregulation of HINT2 expression." (PMID 38546629, 2024). "In the present study we demonstrate that transcriptional reprogramming of Atp2a2 and Myh7 genes in pressure overload-induced cardiac hypertrophy and failure is associated with significant epigenetic changes, modifying chromatin dynamics at the promoter regions of these crucial genes." (PMID 25181347, 2014). "The up-regulation of miR-328 expression suppresses its target gene SERCA2a (ATPase Sarcoplasmic/Endoplasmic Reticulum Ca2+ Transporting 2) in cardiac myocytes to indirectly activate the calcineurin/NFATc3 signaling pathway, leading to cardiac hypertrophy." (PMID 28558735, 2017). "Down-regulation of calcium handling genes (e.g., Pln, Atp2a2) and adult forms of sarcomeric genes (e.g., Actc1 and Tpm1) is another gene expression signature of cardiac hypertrophy and failure." (PMID 28861005, 2017). "To test this possibility, we used a well-established mouse model of cardiac hypertrophy and HF induced by transverse aortic constriction, and analyzed chromatin marks at the Atp2a2 and Myh7 promoters after one or eight weeks of pressure overload." (PMID 25181347, 2014). "Moreover, AngII stimulates cardiac hypertrophy induced by calcium overload through the impaired function of ATP2a2, an ATPase that pumps calcium into the sarcoplasmic reticulum lumen, which is down-regulated in infarcted tissue." (PMID 36979032, 2023). "Both groups of mice developed a comparable degree of cardiac hypertrophy in response to TAC, as shown by similarly enhanced HW/TL ratio, embryonic gene expression (decrease in Myh6 and Atp2a2, increase in Myh7 and Acta1 mRNA) and cardiomyocyte size." (PMID 35013221, 2022).
diabetes (21 papers, 2010 to 2025). "It is currently not known whether DD patients carry other risk factors for the development of diabetes irrespective of ATP2A2 mutation status." (PMID 32042314, 2020).
schizophrenia (19 papers, 2011 to 2025). A major psychotic disorder characterized by abnormalities in the perception or expression of reality. "More recently, ATP2A2/SERCA2 is reportedly linked to mental disorders, such as bipolar disorder and schizophrenia), suggesting its potentially important roles in brain functions." (PMID 39974971, 2025). "Fine-mapping of the significant loci from the PGC schizophrenia phase 3 genome-wide association study identified an intronic variant of ATP2A2 as highly probable of being causal." (PMID 37881554, 2023). "A large-scale genome-wide association study discovered that ATP2A2 was significantly associated with schizophrenia, indicating that the ATP2A2 was a risk gene for schizophrenia (Schizophrenia Working Group of the Psychiatric Genomics Consortium, 2014)." (PMID 34659328, 2021). "Abnormalities in EEG delta waves during sleep have been reported in schizophrenia patients and its relevance with ATP2A2 has been implicated." (PMID 34104969, 2021). "Most notably, mutations in both DRD2 and ATP2A2 have been identified by GWAS as common risk variants in schizophrenia." (PMID 34955759, 2021). "Recently, it was found that loss-of-function mutations of ATP2A2 confer a risk of neuropsychiatric disorders including depression, bipolar disorder and schizophrenia." (PMID 34104969, 2021). "Recent evidence has shown that loss of function (LOF) mutations of ATP2A2 confer an increased risk for psychoses including bipolar disorder and schizophrenia." (PMID 34104969, 2021). "Similarly, a GWAS of schizophrenia also showed an association with ATP2A2 and schizophrenia." (PMID 34104969, 2021). "In addition, a genome-wide association study found an association between ATP2A2 and schizophrenia." (PMID 34104969, 2021). "We generated and analyzed Atp2a2 brain-specific heterozygous KO mice to model bipolar disorder and schizophrenia." (PMID 34104969, 2021). "The ATP2A2 locus, the human homologue of Serca2, was also identified as one of 108 loci meeting genome-wide significance for association with SCZ by the Schizophrenia Working Group of the Psychiatric Genomics Consortium." (PMID 34685659, 2021). "Finally, like ATP2A2, DRD2 is one of 108 loci that meets genome-wide significance for association with SCZ, per the Schizophrenia Working Group." (PMID 34685659, 2021). "Thus, a brain-specific heterozygous KO mouse of Atp2a2 would be more useful to study bipolar disorder and schizophrenia." (PMID 34104969, 2021). "Collectively, our results show that the Atp2a2 hetero cKO mice could be a useful model for some facets of mood disorders and schizophrenia along with other currently used mouse models." (PMID 34104969, 2021).
Obesity (12 papers, 2014 to 2026). Accumulation of substantial excess body fat. "Dysregulation of this network or mutations in the ATP2A2 gene have been linked to hereditary myopathies, while SERCA2 dysfunction is also a key driver of muscle atrophy and insulin resistance in pathological conditions such as chronic inflammation and obesity." (PMID 41940033, 2026). "On the other hand, the mRNA expression of ATP2A2 (SERCA2) was slightly elevated in people with grade 1 and 2 obesity but down-regulated in people with grade 3 obesity and obesity with type 2 diabetes." (PMID 40199326, 2025).
cardiomyopathy (11 papers, 2011 to 2025). A disease of the heart muscle or myocardium proper. "ATP2A2 (ATPase sarcoplasmic/endoplasmic reticulum Ca2+ transporting 2) was identified as a target of miRNA-323-3p, which could be involved in and have an impact on cardiomyopathy progression." (PMID 32291635, 2020).
dilated cardiomyopathy (8 papers, 2016 to 2024). Cardiomyopathy which is characterized by dilation and contractile dysfunction of the left and right ventricles. "Next, the Tpm3 and Atp2a2 were core genes in pathway “cardiac muscle contraction”, “dilated cardiomyopathy” and “hypertrophic cardiomyopathy”." (PMID 36817606, 2023). "In contrast to the moderate phenotypes in adult Atp2a2 knockout mice, CASAAV-based Atp2a2 knockout in neonates resulted in acute dilated cardiomyopathy and death within 3 weeks after AAV administration." (PMID 35433671, 2022). "Dilated cardiomyopathy (DCM) pathway, including Lama2, Tnnt2, Actg1, Atp2a2, Gnas, Tpm3, Itga6, Tpm1, and Pln, was enriched in the KEGG pathway." (PMID 37858115, 2023).
colon carcinoma (6 papers, 2012 to 2025). "Reports have confirmed that abnormal expression of ATP2A2 is involved in the occurrence of lung cancer, the differentiation of squamous cancer cells, and early events in the development of colon cancer." (PMID 41300841, 2025).
colorectal cancer (6 papers, 2015 to 2021). A primary or metastatic malignant neoplasm that affects the colon or rectum. "For example, in colorectal cancer (CRC) increased SERCA2 transcripts correlate with tumor node metastasis or higher tumor grade, while decreased ATP2A2 mRNA abundance is measurable in transformed thyroid cells." (PMID 33407740, 2021).
hypertrophic cardiomyopathy (6 papers, 2013 to 2025). A condition in which the myocardium is hypertrophied without an obvious cause. "The ‘Hypertrophic cardiomyopathy’ pathway was also significantly enriched, including genes such as ATPase sarcoplasmic/endoplasmic reticulum Ca2+ transporting 2 (ATP2A2) and others already identified in the PPI network (e.g., TPM1 and ACTC1)." (PMID 40559872, 2025). "The present results showed that many genes significantly altered in cell development and hypertrophic cardiomyopathy by overexpressed atrogin-1, Myh6, Serca2 (ATP2A2) and Prkcz were significantly up-regulated, whereas Itga3 (also known as CD49c) and Foxa2 were down-regulated.." (PMID 23335977, 2013).
Hypertension (5 papers, 2014 to 2025). The presence of chronic increased pressure in the systemic arterial system. "Estradiol, 17-beta-isomer of estradiol, has the shortest path from its target NOS2 to hypertension through NOS2, ATP2A2, and ‘calcium ion binding’ in muscle cells in myocardium." (PMID 28790372, 2017).
metabolic syndrome (5 papers, 2016 to 2025). A cluster of metabolic risk factors for CARDIOVASCULAR DISEASES and TYPE 2 DIABETES MELLITUS. "We showed that lymphatic muscle cells express SERCA2 (also known as ATP2A2) isoforms, SERCA2a and SERCA2b, but only the levels of SERCA2a were reduced in a high-fructose diet rat model of metabolic syndrome." (PMID 40600271, 2025).
Alzheimer disease (4 papers, 2023 to 2025). A progressive, neurodegenerative disease characterized by loss of function and death of nerve cells in several areas of the brain leading to loss of cognitive function such as memory and language. "Besides, Atp2a2 played a crucial role in pathway of “Alzheimer disease”." (PMID 36817606, 2023).
breast carcinoma (3 papers, 2018 to 2022). "Similarly, the ATP1A1 lever was elevated and affected breast cancer patients’ survival, whereas ATP2A2 seemed to be neutral in respect to survival." (PMID 34684111, 2021). "ATP2A2 expression levels were not altered in any of the subclasses of breast cancer vs. normal samples." (PMID 34684111, 2021).
glioma (3 papers, 2013 to 2022). A benign or malignant brain and spinal cord tumor that arises from glial cells (astrocytes, oligodendrocytes, ependymal cells). "Several genes down-regulated in BAT such as PRDM2, TCF7L2, RB1CC1, ATP2A2 are involved in the pathogenesis of other type of cancers, but not in gliomas." (PMID 23472076, 2013).
leukemia (3 papers, 2015 to 2022). A malignant (clonal) hematologic disorder, involving hematopoietic stem cells and characterized by the presence of primitive or atypical myeloid or lymphoid cells in the bone marrow and the blood. "TM9SF3 and ATP2A2 were considered as proto-oncogenes in leukemia, triple-negative breast cancer and diffuse astrocytic tumor." (PMID 36733399, 2022).
viral infection (3 papers, 2019 to 2024). "The identification of the novel nonsense ATP2A2 gene variant in this patient with COVID-19 provides valuable insights into the pathogenesis of DD associated with viral infections." (PMID 38428853, 2024).
astrocytoma (2 papers, 2020 to 2023). "Higher ATP2A2 expression is correlated with a better prognosis in patients with astrocytoma, as ATP2A2 can suppress tumor growth." (PMID 37559135, 2023). "High expression of ATP2A2 was identified to be positively correlated with favorable prognosis of astrocytoma." (PMID 32297639, 2020).
COVID-19 (2 papers, 2024). A disease caused by infection with severe acute respiratory syndrome coronavirus 2. "Of interest, we observed decreased levels of ATP2B1 and ATP2B4 in the lungs of COVID-19 patients, while the levels of ATP2A2 were found to increase (Fig. EV1G)." (PMID 38816514, 2024).
glioblastoma (2 papers, 2020 to 2021). The most malignant astrocytic tumor (WHO grade IV). "Additionally, ATP2A2 expression levels are significantly correlated with tumor grade and survival rates, where high ATP2A2 expression has been detected in patients with glioblastoma." (PMID 34684111, 2021).
hypothyroidism (2 papers, 2015 to 2026). Abnormally low levels of thyroid hormone. "Studies in rabbits and mice have shown that it is associated with a reduction in cardiac SERCA2 expression, raising the possibility that the impairment of cardiac function caused by hypothyroidism would be greater in Atp2a2 heterozygous individuals." (PMID 26064889, 2015). "The finding that Atp2a2 heterozygosity does not exacerbate the effects of hypothyroidism in mice may result from the switch in myosin heavy chain (MHC) isoforms from α-MHC to the slower β-MHC, which occurs in hypothyroidism, and is known to be energetically favorable." (PMID 26064889, 2015).
mental disorder (2 papers, 2021 to 2025). A disease that has its basis in the disruption of mental process. "However, the mechanism of how ATP2A2 contributes to vulnerability to these mental disorders is unknown." (PMID 34104969, 2021).
breast diseases (1 paper, 2025). "The results of GSEA revealed that ARRDC1 and ATP2A2 are co-enriched in multiple signaling pathways closely associated with the pathogenesis of breast diseases in both BBD and BC." (PMID 41300841, 2025). "The findings of this study indicate that the expression of ATP2A2 is upregulated in patients with breast diseases (especially BC), and the overexpression of ATP2A2 is associated with a poorer survival rate." (PMID 41300841, 2025). "In conclusion, this study implemented bioinformatics and ML algorithms to ascertain two key biomarkers (ARRDC1 and ATP2A2) for screening breast diseases, including BBD and BC." (PMID 41300841, 2025). "Consequently, the ATP2A2 gene exhibits potential as a biomarker and therapeutic target for breast diseases." (PMID 41300841, 2025). "In addition, the hormone signaling pathways jointly participated in by ARRDC1 and ATP2A2 are crucial in the development of breast diseases." (PMID 41300841, 2025). "However, functional studies on the ATP2A2 gene in breast diseases remain relatively scarce." (PMID 41300841, 2025).
endometrial cancer (1 paper, 2023). Primary or metastatic malignant neoplasm involving the endometrium (mucous membrane that lines the endometrial cavity). "However, there have been no reports on the involvement of PRMT2, NEK6, NACC1, ATP2A2, and TM4SF19 in endometrial cancer." (PMID 37780629, 2023).
infantile spasms (1 paper, 2025). A rare epilepsy syndrome characterized by onset of epileptic spasms in infants between 2 and 12 months of age, and rarely up to 24 months. "Interestingly, two down-regulated genes in males, Atp2a2 and Cplx2, were up-regulated in females, indicating opposite effects of triggering the infantile spasms in the two sexes." (PMID 40699779, 2025).
oral squamous cell carcinoma (1 paper, 2022). "In particular, ATP2A2 gene inactivation is closely related to oral squamous cell carcinoma." (PMID 35449571, 2022).
prostate carcinoma (1 paper, 2024). A carcinoma that arises from epithelial cells of the prostate gland. "Recovery of Ca2+ signals in prostate cancer cells is dependent on SERCA and the activity of SERCA could be altered with TMCO1 silencing as our LC-MS/MS studies identified SERCA2 (ATP2A2) as an interacting partner with TMCO1." (PMID 39353922, 2024).
psychosis (1 paper, 2021). "Serca2 serves an important role in delta-oscillation generation, and ATP2A2 mutations are associated with psychosis." (PMID 34955759, 2021).